DDX3X (DEAD-box helicase 3 X-linked)
Diseases named in the same sentence as DDX3X in open-access papers (continued):
Sharing a sentence is not in itself a finding about the gene and the disease.
melanoma (27 papers, 2014 to 2025). A malignant, usually aggressive tumor composed of atypical, neoplastic melanocytes. "It was also reported that DDX3X escapes X chromosome inactivation and is preferentially mutated in male melanoma patients, supporting the sex differences observed in this tumor." (PMID 35954483, 2022). "Intriguingly, loss of DDX3X expression directs a proliferative-to-metastatic phenotypic switch in melanoma cells." (PMID 33627125, 2021). "A mutational assessment of 864 melanoma tumours identified DDX3X mutations, most of which might eventually lead to DDX3X loss of expression." (PMID 33627125, 2021). "Loss of DDX3X disrupts MITF regulation, prompting melanoma cells to transition from a proliferative to a more invasive, metastatic phenotype." (PMID 39823244, 2025). "Mutations in DDX3X also correlate with increased phosphorylation of STAT3 and p42/p44 MAPK, contributing to chemoresistance in melanoma." (PMID 39823244, 2025). "An unbiased translational screening of melanoma phenotypes uncovered the microphthalmia-associated transcription factor (MITF) as a key downstream target of DDX3X in melanomas." (PMID 38539466, 2024). "However, DDX3X has also been shown to suppress immune responses by interacting with the NF-κB subunit p65 or by enhancing the cytoplasmic accumulation of endogenous dsRNA to boost the melanoma-differentiation-associated gene 5 (MDA5)-mediated dsRNA-sensing pathway." (PMID 39759074, 2024). "Due to its versatile functionality in cellular biology, DDX3X has been investigated in a variety of cancer types such as melanoma, breast, and prostate cancers; however, its role across cancer types is conflicting." (PMID 38539466, 2024). "As a consequence, the loss of DDX3X altered MITF translational regulation, triggering a proliferative-to-metastatic phenotypic switch in melanoma cells." (PMID 35954483, 2022). "In melanoma, DDX3X promotes the mRNA translation of MIFT, a regulator of development in various cell types that is correlated with less invasive tumors when highly expressed." (PMID 35954483, 2022). "Importantly, 82% of all DDX3X mutations, including all truncating mutations, were detected in male patients, implying that DDX3X might play an important role in the progression of melanoma in males." (PMID 33627125, 2021). "DDX3X was found to regulate MITF protein levels and mutations were present in 5.8% of their melanoma cohort." (PMID 35008286, 2021). "MITF, which is strongly correlated with a less invasive and more proliferative expression signature in melanoma, was identified as a direct translational target of DDX3X." (PMID 33627125, 2021). "Recently, a new study showed that CD133+ murine melanoma cells express DDX3X antigen which is immunogenic and able to protect melanoma growth in T-cell dependent manner." (PMID 28137308, 2017). "Our previous proteome analyses identified DDX3X as a protein preferentially expressed in purified CD133+ B16 melanoma cells, which possessed cancer stem cell (CSC)-like properties." (PMID 25343452, 2014). "Recently, we found DDX3X as the protein that was preferentially expressed in murine melanoma with cancer stem cell (CSC)-like phenotypes by proteome analysis." (PMID 25343452, 2014). "We recently reported that DDX3X expression is upregulated in the CD133+ melanoma subpopulation, which possesses CSC-like properties, such as tumor sphere formation and high tumorigenicity." (PMID 25343452, 2014). "Additionally, DDX3X appears to regulate the proliferation and migration of melanoma cells by translational repression of the oncogene MITF." (PMID 39185415, 2024). "DDX3X is described as a repressor of tumorigenesis in melanoma and NK/T-cell lymphoma." (PMID 35954483, 2022). "DDX3X can dictate translation reprogramming and metastasis in melanoma." (PMID 35406721, 2022). "Moreover, reduced DDX3X expression correlates with tumor progression and poor prognosis in melanoma patient cohorts." (PMID 35406721, 2022).
melanoma (continued). "DDX3X may play a role in this disparity and perhaps future studies will identify other sex-chromosome-specific genes affecting survival and melanoma metastasis." (PMID 35008286, 2021). "DDX3X is a major immunogenic protein in CD133+ melanoma cells." (PMID 33627125, 2021). "The second group comprised of serine/threonine-protein phosphatase 6 catalytic subunit (PPP6C), DEAD-box helicase 3 X-linked (DDX3X), phosphatase and tension homology (PTEN), and ras-related C3 botulinum toxin substrate 1 (RAC1) genes, which showed mutations in 5 to 9% melanoma tissues." (PMID 33256110, 2020). "DDX3X is an x-linked RNA helicase, which has been linked to post-translational regulation of MITF (Microphthalmia-associated Transcription Factor) expression and development of melanoma metastasis and therapy resistance." (PMID 32731355, 2020). "The six pan-cancer X-linked genes (ATRX, CNKSR2, DDX3X, KDM5C, KDM6A, and MAGEC3) were examined for their association with melanoma survival by comparing the survival of all patients with the expression of genes above (high) or below (low) median expression levels." (PMID 32731355, 2020). "Notably, higher expression of DDX3X and KDM6A was associated with better melanoma-specific survival in all patients (only when analyzed on a continuous scale for the former)." (PMID 32731355, 2020). "Further insights into RNA helicases reveal the role of DDX3X in enhancing the translation of MITF, a transcription factor that suppresses melanoma invasiveness when highly expressed." (PMID 39823244, 2025). "By promoting mRNA translation, DDX3X can increase MITF protein levels and alter metastatic potential and response to targeted melanoma therapies." (PMID 38539466, 2024). "In addition to CSDE1, several RBPs have been shown to play roles in melanoma progression, including CELF, CPEB4, IGF2BP1, IGF2BP3, NOVA1 and DDX3X, among others." (PMID 38396995, 2024).
prostate carcinoma (14 papers, 2016 to 2026). A carcinoma that arises from epithelial cells of the prostate gland. "Malfunctions of DDX3X have been implicated in multiple cancers, including brain cancer, leukemia, prostate cancer, and head and neck cancer." (PMID 38539466, 2024). "DDX3X overexpression has been reported in prostate cancers, and overexpression was found to be directly associated with high Gleason scores." (PMID 31906196, 2019). "In particular, cytoplasmic DDX3X levels in prostate cancer tissue samples have been associated with cancer metastasis status, and repression of DDX3X via genetic and pharmacologic methods reduces cell motility." (PMID 31906196, 2019). "It has been effective in inhibiting DDX3X helicase activity in breast, lung, and prostate cancers." (PMID 38539466, 2024). "Both prostate cancer and Ewing sarcoma are characterized by an elevated expression of DDX3X." (PMID 35954483, 2022).
glioma (13 papers, 2015 to 2024). A benign or malignant brain and spinal cord tumor that arises from glial cells (astrocytes, oligodendrocytes, ependymal cells). "For example, high expression levels of DEAD-box helicase 3 X-linked (DDX3X) encoding adenosine triphosphate (ATP)-dependent RNA helicase are correlated with poor survival outcome in human gliomas." (PMID 33451362, 2020). "Especially in glioma, higher levels of AEP were associated with higher levels of nuclear DDX3X, which supports the potential pathological importance of AEP cleavage-induced nuclear DDX3X." (PMID 37988165, 2023). "All together, these data verified that tDDX3X-C produced by AEP cleavage aggregates in the nucleus due to the absence of the N-terminal NES and confirmed the positive relationship between AEP and nuclear DDX3X in glioma." (PMID 37988165, 2023). "Although DDX3X was present in both the cytoplasm and nucleus in glioma, intranuclear DDX3X was significantly higher in HGG than in LGG." (PMID 37988165, 2023). "Even if the role of DDX3X in human gliomas is not completely understood, its expression is significantly higher in glioma cells compared to normal brain tissue." (PMID 34771731, 2021). "In some of the genes that we identified, a cancer-related function was already known, e.g., DDX3X has been shown to have poor prognosis in glioma." (PMID 34621669, 2021). "Molecular studies including qRT-PCR, Western blotting, and IHC staining further confirmed that DDX3X is over expressed in high-grade gliomas." (PMID 26184164, 2015). "DDX3X protein production in human glioma cell lines and normal brain tissue was quantitated by Western blot analysis." (PMID 26184164, 2015). "Theoretically, the examination of DDX3X protein expression in several pairs of glioma with different grades is important." (PMID 26184164, 2015). "DDX3X protein production in human gliomas tissues and normal brain tissues was checked by IHC staining of tissue microarray." (PMID 26184164, 2015). "Validation of DDX3X-regulated genes found that DDX3X protein highly expresses in human glioma cells and correlates the protein level of SP1, and ESR1." (PMID 26184164, 2015). "DDX3X protein significantly overexpressed in human glioma cell lines, including LN229, U87MG, GBM8401 and U118MG, compared to normal brain tissue." (PMID 26184164, 2015). "The quantitative RT-PCR showed DDX3X mRNA expression is significantly higher in glioma cells compared to normal brain tissue." (PMID 26184164, 2015). "The expression of DDX3X was significantly increased in glioma cells in comparison with normal brain tissue." (PMID 26184164, 2015). "Alternatively, we have examined DDX3X protein expression in four glioma cell lines and commercially available normal brain lysate to confirm the DDX3X protein expression is really higher in glioma than in non-tumor brain control." (PMID 26184164, 2015). "We further analyzed the correlation of AEP and nuclear DDX3X in glioma tissue microarrays." (PMID 37988165, 2023). "Furthermore, DDX3X mRNA expression and protein production significantly increased in glioma cells compared with normal brain tissue examined by quantitative RT-PCR, and Western blot." (PMID 26184164, 2015). "The DDX3X mRNA expressions were examined in glioma cells by q-RT PCR." (PMID 26184164, 2015). "Western blot reveals DDX3X protein is highly produced in human glioma cell lines." (PMID 26184164, 2015). "Based on this hypothesis, we intended to investigate if DDX3X expression is associated with the survival outcome and WHO pathologic grading in human gliomas." (PMID 26184164, 2015).
glioma (continued). "This study hypothesized that high-grade glioma overexpressed DDX3X." (PMID 26184164, 2015). "Specifically, previous studies described the ability of several molecular markers involved for predicting the prognosis of glioma and these molecular markers include MEOX2, PDIA5, and DDX3X." (PMID 39012280, 2024). "From a pathological point of view, overexpression of DDX3X is positively correlated with pathological classification in glioma, meningioma and PDAC, indicating that DDX3X has the potential to differentiate the degrees of pathological classification of tumours." (PMID 33627125, 2021). "The DDX3X protein highly expresses in human glioma cells also correlates with the protein level of SP1, and ESR1 in human glioma cell lines including LN229, U87MG, GBM8401 and U118MG as compared with normal brain tissue." (PMID 26184164, 2015). "Taken together, DDX3X expression level positively correlates with WHO pathologic grading and poor survival outcome, indicating that DDX3X is a valuable biomarker in human gliomas." (PMID 26184164, 2015). "The low-grade glioma cell line, LN229, and WHO grade IV glioma cell lines including U87MG, GBM8401, and U118MG were applied to compare DDX3X expression with normal brain." (PMID 26184164, 2015). "The present studies suggest that DDX3X expression is significantly higher in patients with high-grade gliomas than in those with non-tumor brain controls and low-grade gliomas." (PMID 26184164, 2015). "However, the role of DDX3X in defining the pathological grading and survival outcome in patients with human gliomas is not yet clarified." (PMID 26184164, 2015). "DDX3X protein overexpressed in high-grade gliomas (WHO grade IV, and III) compared with low-grade gliomas, or non-tumor brain tissue control." (PMID 26184164, 2015). "However, the role of DDX3X in determining the survival outcome and WHO pathologic grading of human gliomas is not yet clarified." (PMID 26184164, 2015).
Burkitt lymphoma (12 papers, 2015 to 2025). A rare form of malignant mature B-cell non-Hodgkin lymphoma. "This ectopic DDX3Y expression has been proposed to contribute to the sexual dimorphism seen in Burkitt lymphoma and other male-skewed cancers with frequent DDX3X mutations." (PMID 39975375, 2025). "DDX3X mutations have been detected in various types of lymphoma including ~30% cases of Burkitt lymphoma, which has a 3:1 male vs. female incidence ratio." (PMID 39975375, 2025). "Loss-of-function mutations of DDX3X are also frequent in B cell lymphomas including Burkitt lymphoma and DLBCL." (PMID 36845680, 2023). "The mutation of DDX3X has been reported in Burkitt lymphoma, chronic lymphocytic leukemia, and natural killer T-cell lymphoma." (PMID 36497332, 2022). "DDX3X has been reported to be mutated in Burkitt's lymphoma." (PMID 26377837, 2015). "Mutations or loss of DDX3X are known in DLBCL, Burkitt’s lymphoma, cutaneous T-cell lymphoma, and NK/T-cell lymphoma." (PMID 37705009, 2023). "DDX3X is a tumor-suppressing gene that is recurrently mutated in Burkitt lymphoma and EZH-DHIT + B cell lymphomas, and such mutation results in the truncation or loss of DDX3X." (PMID 35303910, 2022). "Recent mutational cartography efforts in Burkitt lymphoma identified additional recurrent mutations in GNA13, RET, PIK3R1, DDX3X, FBXO11, and the SWI/SNF genes ARID1A and SMARCA4." (PMID 34283060, 2021). "DDX3X inhibition effectiveness in vivo was evaluated through a dissemination model which emulates human Burkitt lymphoma (BL)." (PMID 40772229, 2025). "The Raji cell line, which carries a catalytically inactive DDX3X and relies on wild-type DDX3Y was chosen because it represents a typical case of Burkitt lymphoma, in which a mutant DDX3X is present alongside DDX3Y, both potentially contributing to the malignancy." (PMID 40772229, 2025). "As sex chromosome‐specific genes, the functional difference between DDX3X and DDX3Y might explain the gender differences in the incidence rate of Burkitt lymphoma." (PMID 36971051, 2023).
colon cancer (12 papers, 2015 to 2025). "Consistent with our previous findings, J10 treatment effectively decreased DDX3X protein levels and showed comparable cytotoxicity with RK-33 in pancreatic cancer and colon cancer." (PMID 40885716, 2025). "In HCT116 and HT-29 colon cancer cells, inhibition of DDX3X reduces proliferation, presumably by involving the Wnt pathway." (PMID 29899866, 2018). "The role of DDX3X in this kind of cancer has not been assessed, but it has been shown that in gastric, prostate and colon cancer cell lines, the interaction of DDX3X with YY1 is mediated by the circular DNA circ-CTNNB1, promoting tumor proliferation through the deregulation of the β-catenin axis." (PMID 35954483, 2022). "In HCT116 colon cancer cells, we detected 44% increase in endogenous DDX3Y following siRNA-mediated knockdown of DDX3X." (PMID 39975375, 2025).
autism (11 papers, 2020 to 2025). Persistent deficits in social interaction and communication and interaction as well as a markedly restricted repertoire of activity and interest as well as repetitive patterns of behavior. "DDX3X is also recognized as a single-gene driver for rare syndromes associated with epilepsy, autism, and developmental disorders." (PMID 41393511, 2025). "Xi-expressed gene DDX3X is among the most conistently associated risk genes for autism and intellectual disability." (PMID 40964017, 2025). "Nonetheless, SRS scores indicated that many individuals with DDX3X variants exhibit autism characteristics, with the range of SRS scores aligning with previous reports." (PMID 35536379, 2023). "DDX3X mutations can impair RNA helicase activity and disturb RNA metabolism, thus leading to the pathogenesis of autism, brain malformations, and epilepsy." (PMID 36059957, 2022). "In the context of this literature, our findings suggest that the social vulnerabilities observed in association with DDX3X variants reflect autism characteristics shared amongst girls and women with monogenic ID; however, further work is required to confirm this." (PMID 35536379, 2023). "Remarkably, two of the PTCHD1-specific interactors are independently associated with autism (DYRK1A and DDX3X) and 11 have been previously identified as PTCHD1 interactors in mouse brain lysates." (PMID 36769003, 2023). "Indeed, DDX3X mutations have been identified in ASD cohorts, and DDX3X is considered a high-confidence Autism gene." (PMID 35762573, 2022). "DDX3X is listed as strong ASD candidate (category 2) in the SFARI autism gene database." (PMID 32012899, 2020). "Autism genes are strongly represented amongst these paired genes, with two (NLGN4Y, USP9Y) expressed from Chr Y, and seven (DDX3X, KDM5C, KDM6A, NLGN4X, TBL1X, USP9X, and ZFX) from Xi." (PMID 40964017, 2025).
HIV-1 infection (11 papers, 2014 to 2025). The type species of lentivirus and the etiologic agent of acquired immunodeficiency syndrome (AIDS). "Mechanistically, DDX3X specifically recognizes abortive RNA generated during HIV-1 infection, activating the type I interferon signaling pathway via the MAVS, thereby inducing dendritic cell maturation and initiating adaptive immune responses." (PMID 40606174, 2025). "DDX3X specifically recognizes abnormal short - chain RNAs generated during HIV-1 infection." (PMID 40606174, 2025). "During HIV-1 infection, the dual role of DDX3X in utilizing both proviral and antiviral capacities provides insight into its complexity and the various roles DDX3X might play in establishing immunity." (PMID 35874614, 2022). "Additionally, we determined that IL-6, a cytokine regulated by DDX3X and ZC3HAV1, exhibits changes in protein expression levels during both active and persistent HIV-1 infection." (PMID 40429887, 2025). "Finally, we determined that IL-6—a cytokine regulated by DDX3X and ZC3HAV1—also changes its expression levels during the different stages of HIV-1 infection in microglia." (PMID 40429887, 2025).